S100A8 (S100 calcium binding protein A8)
Diseases named in the same sentence as S100A8 in open-access papers (continued):
Sharing a sentence is not in itself a finding about the gene and the disease.
lymphoma (13 papers, 2017 to 2025). A malignant (clonal) proliferation of B- lymphocytes or T- lymphocytes which involves the lymph nodes, bone marrow and/or extranodal sites. "The results revealed that a neutrophil count <1x109/L, high S100A8/9 expression, and lymphoma-associated sHLH (LHLH) were risk factors for poor prognosis in patients with sHLHa (P < 0.05)." (PMID 40735470, 2025). "The levels of S100A8/A9 in saliva can help differentiate the subgroups of Sjögren’s syndrome with lymphoma risk." (PMID 35371990, 2022). "Interestingly, it has been observed that salivary S100-A9, in an S100-A8/S100-A9 complex, is significantly increased in pSS patients at risk of developing lymphoma." (PMID 35409074, 2022). "Interestingly, genes known to be implicated in lymphoma biology, such as S100A8, S100A9 and KITLG, were included amongst those regulated by calcitriol." (PMID 33466695, 2021). "The protein levels of S100A8 in malignant lymphomas were higher than in normal lymph nodes." (PMID 38361783, 2024). "In a recent study on relapsed or refractory T-cell acute lymphoblastic leukemia/lymphoma patients undergoing anti-CD7 CAR-T therapy, scRNA-seq demonstrated high expression of S100A8 in various T cell subpopulations in the relapsed patients." (PMID 38035111, 2023).
Stroke (13 papers, 2016 to 2026). Sudden impairment of blood flow to a part of the brain due to occlusion or rupture of an artery to the brain. "Previous studies have shown an association between systemic plasma levels of S100A8/A9 at baseline and functional outcomes 3 months after stroke with mild to moderate severity." (PMID 40656637, 2025). "The role of systemic plasma levels of S100A8/A9 in stroke-related inflammation and its association with clinical outcome lacks sufficient data." (PMID 40656637, 2025). "This study explores the role of S100A8/A9, a neutrophil derived plasma biomarker, in stroke-related inflammation and its association with clinical outcomes." (PMID 40656637, 2025). "The aim of this study was to investigate the association between systemic plasma levels of S100A8/A9 and neutrophil counts during the acute phase of stroke in patients with moderate to severe AIS." (PMID 40656637, 2025). "Additionally, we aimed to explore the relationship between plasma S100A8/A9 levels and functional outcome 3-months after-stroke, assessing its role in inflammation-associated morbidity in AIS." (PMID 40656637, 2025). "Moreover, the observed association between systemic plasma levels of S100A8/A9 and mortality within three months post stroke underscores the potential as an indicator of poor or limited prognosis." (PMID 40656637, 2025). "Moreover, S100A8/A9 can induce the formation of procoagulant platelets through GPIb-alpha and thereby foster fibrin formation and immune-driven thrombosis in diseases associated with high levels of S100A8/A9 e.g. stroke, as shown in our study." (PMID 40656637, 2025). "Given our previous work showing that S100A8/A9 promotes myelopoiesis, we pharmacologically inhibited S100A8/A9 to determine if this would modulate stroke-induced myelopoiesis." (PMID 41782870, 2026). "The expression of S100A8 increased 24 h after stroke induction in the ipsilateral hemisphere vs. the contralateral hemisphere (p < 0.01) and versus all the other days of the experiment (p < 0.01 for 6 h and 7 d and p < 0.001 for 3 d)." (PMID 40332314, 2025). "The age-related cerebrovascular diseases for the hub genes and S100a8 included cerebrovascular disorders, stroke, brain ischemia, ischemic attack, cerebral infarction, cerebral hemorrhage, and intracranial hemorrhage." (PMID 37033380, 2023). "In contrast, MG6 was defined as the “neutrophil-like” subset, with upregulated expression of Cxcr2, S100a8, Il1b, and Mmp9, perhaps representing a stroke-specific state of microglia in the aged brain after stroke." (PMID 36052339, 2022). "Second, systemic plasma levels of S100A8/A9 were measured at a single point in time after stroke." (PMID 40656637, 2025). "Notably, the Neu_0 subgroup predominated among stroke neutrophils at 1 h, 24 h, and 7 days, exhibiting heightened expression of chemotactic genes such as Lrg1, Fos, Sell, Lfb, and S100a8." (PMID 38988493, 2024). "Third, pre-stroke systemic plasma levels of S100A8/A9 were unknown." (PMID 40656637, 2025). "To understand the role of S100A8/A9 in modulating stroke-induced myelopoiesis, we administered a small molecule inhibitor of S100A8/A9, ABR-215757, before and after stroke." (PMID 41782870, 2026). "Calcium-binding proteins—S100A8 and S100A9—were significantly elevated in the stroke-covered hemispheres." (PMID 40332314, 2025). "In our study, the enhanced expression of the S100A8 and S100A9 genes was already noticed in the ipsilateral hemisphere 24 h after stroke." (PMID 40332314, 2025). "Since S100A8 and S100A9 also exhibit chemotactic properties by recruiting immune cells, it can be assumed that their increased expression 24 h after stroke in pigs also contributes to the development of the inflammatory response." (PMID 40332314, 2025).
Stroke (continued). "We identified Il-1β, Ccl2, Cybb, Wnt9b, as well as some pathway-specific genes such as S100a8 and S100a9 (IL-17 signaling) among the common pro-inflammatory and signaling molecules whose expression was affected by higher TMAO levels in post-stroke animals." (PMID 37175797, 2023). "Previous studies have shown that S100A8 is involved in the pathophysiology of diverse diseases in the CNS, such as TBI and stroke." (PMID 33613176, 2020). "Among them, MG6 cells expressed high levels of Cxcr2, S100a8, interleukin (IL)‐1β, and matrix metallopeptidase 9 (MMP9), demonstrating a unique “neutrophil‐like” phenotype and were considered to represent a stroke‐specific state of microglia in the aged brain after stroke." (PMID 40843131, 2025).
breast tumor (12 papers, 2012 to 2025). "The mRNA levels of S100A8 were significantly lower but that of S100A9 was significantly higher in ER+-breast tumor than in ER--breast tumor." (PMID 29416786, 2018). "Concerning the gene expression pattern of grade III breast tumors, the S100A8 gene, the top upregulated gene in grade III compared to low-grade tumors, appeared to be a central gene in the main regulatory network." (PMID 25391423, 2015). "S100A8 overexpression in high-grade breast tumors in comparison to low-grade tumors has been previously reported and associated with poor prognosis, poor tumor differentiation, LVI, and node metastasis when co-expressed with S100A9." (PMID 25391423, 2015). "Future studies are aimed at determining if S100A8/A9 levels and CD11b+Gr-1+ numbers remained unchanged or were variable throughout the course of breast tumor development." (PMID 22946998, 2012). "Ghavami and colleagues demonstrated that S100A8/S100A9 proteins used at a concentration of 10 μg/mL induced growth of several breast tumor cell lines including MCF-7, MDA-MB231, and SHEP, whereas at higher concentrations it did not enhance cellular proliferation." (PMID 36923707, 2023). "Interestingly, in conformity with our cell line RNA-seq data, 4T1.2 primary breast tumors showed increased expression of S100A8 compared to 4T1 primary breast tumors." (PMID 34072157, 2021). "Additionally, Pn is known to promote myeloid-derived suppressor cells (MDSC)-mediated pulmonary premetastatic niche formation during breast tumor metastasis through S100A8/9 and LOX." (PMID 34680221, 2021). "Aiming at further characterizing the significance of S100A8 and S100A9 in breast malignancy, we defined their expression pattern among the different breast tumor subclasses." (PMID 35655319, 2022). "Previous research also found that MDSCs from CCL5-knockout mice with breast tumors expressed less NOS2 and S100A8/9 and showed an immune-stimulatory phenotype." (PMID 34566958, 2021). "Lung metastatic lesion showed no further increased expression of S100A8 compared to 4T1.2 primary breast tumors." (PMID 34072157, 2021). "In addition, we found increased levels of S100A8 and S100A9 in TNBC and HER2-positive BC subtypes compared to Luminal-A and Luminal-B breast tumor subgroups, respectively, and we also highlight a strong correlation between S100A8 and S100A9 gene expression levels in TNBC." (PMID 35655319, 2022). "Of note, our bioinformatics investigation has revealed that S100A8 and S100A9 are greatly expressed in breast tumor tissues rather than in its normal counterpart." (PMID 35655319, 2022).
pneumonia (12 papers, 2017 to 2025). An acute, acute and chronic, or chronic inflammation focally or diffusely affecting the lung parenchyma, caused by an infection in one or both of the lungs (by bacteria, viruses, fungi, or mycoplasma.). "The deficiency of S100A8/A9 in mice could promote the progression of pneumonia caused by Staphylococcus aureus infection." (PMID 36611779, 2023). "It was reported that deficiency of S100A8/A9 in mice could promote the progression of pneumonia caused by bacterial infection." (PMID 32391052, 2020). "This underscores the significance of the hyper-inflammatory cell subsets and molecules (CXCL8 and S100A8/A9) as possible therapeutic targets for mitigating the immunopathogenesis seen in severely infected pneumonia patients." (PMID 39757231, 2025). "Cell-type deconvolution of preoperative RNA-sequencing revealed elevated S100A8/9-high neutrophils alongside reduced naïve CD4 T-cells in those later developing pneumonia." (PMID 37497667, 2024). "Most studies have shown that in tumors and inflammatory diseases, such as in children with pneumonia, cell damage or other inflammatory factors such as IL-17A can activate the expression of S100a8/a9 through the IL-17 signaling pathway." (PMID 35741040, 2022). "Also, high levels of S100A8/A9 have been shown to increase disease severity in mice with induced pneumonia, by aiding in bacterial growth." (PMID 29180999, 2017). "The percentage of MDSCs in PBMCs and the representative effectors, including Arg-1, S100A8/A9 and S100A12, were compared between the pneumonia group and the stable group." (PMID 35242775, 2022). "The frequency of MDSCs and effectors, including arginase-1, S100A8/A9, and S100A12, were significantly increased in the pneumonia group compared with the stable group." (PMID 35242775, 2022). "In the progression of severe pneumonia, rhubarb can significantly protect the intestinal barrier, promote the repair of AT2 cells, and inhibit the accumulation of CD11bLy6G + variable aberrant neutrophils by regulating the S100A8 protein." (PMID 40342990, 2025). "Meanwhile, children with pneumonia infected with bacteria had higher serum S100A8/A9 levels than those with non-infectious pneumonia." (PMID 37180431, 2023). "To analyse the effects of S100A8/A9 and its counterreceptor TLR4 on platelets during acute pneumonia, we examined neutrophil recruitment in global S100A9−/− and conditional TLR4PF4Cre+ mice upon intratracheal infection with the clinically relevant pathogen K. pneumoniae." (PMID 36497202, 2022). "However, the S100A8/A9 levels in children with CAP showed more significant elevation than in the patients with non-infection pneumonia." (PMID 37180431, 2023). "The S100A8/A9 levels increased in children with CAP and patients with non-infection pneumonia." (PMID 37180431, 2023).
acute coronary syndrome (11 papers, 2009 to 2025). Signs and symptoms related to acute ischemia of the myocardium secondary to coronary artery disease. "Increased S100A8/A9 were found to be associated with thrombus formation in acute coronary syndrome (ACS)." (PMID 36874092, 2023). "Elevated concentration of S100A8/9 in coronary artery blood is associated with thrombosis in acute coronary syndrome (ACS) patients and leukocyte activation." (PMID 37217870, 2023). "In addition, elevated S100A8/A9 plasma concentrations are an independent risk predictor for cardiovascular events in both healthy individuals and patients with acute coronary syndrome." (PMID 26799323, 2016). "Plasma S100A8/A9 was found to be highly increased during the ischemic event in acute coronary syndrome patients compared with stable angina or with individuals with angiographically assessed normal coronary artery morphology." (PMID 24453429, 2013). "In addition, S100A8 also possessed a prognostic value, because acute coronary syndrome patients with elevated S100A8 levels exhibited a higher risk of adverse cardiovascular events." (PMID 35365066, 2022).
acute lymphoblastic leukemia (11 papers, 2017 to 2025). Leukemia with an acute onset, characterized by the presence of lymphoblasts in the bone marrow and the peripheral blood. "Elevated expression of S100A8/S100A9 caused glucocorticoid resistance in MLL rearranged infant acute lymphoid leukemia and negatively associated with BCL2 inhibitor venetoclax in AML." (PMID 34485305, 2021). "In AML2 and AML3, the upregulated genes contained S100A8 and S100A9, which are known to be poor prognostic indicators in AML, and elevated expression of the heterodimer S100A8/S100A9 was previously reported to cause glucocorticoid resistance in MLL-rearranged infant acute lymphoid leukaemia cells." (PMID 37615858, 2024). "Therefore, in this work, we researched whether elevated concentrations of HMGB1 and S100A8 in children with acute lymphoblastic leukemia are associated with the presentation of systemic inflammatory response syndrome." (PMID 40868835, 2025). "For instance, S100A8/A9 heterodimers have been shown to drive GSDMD-dependent pyroptosis in acute lymphoblastic leukemia (ALL), while FLOT1 promotes AML progression through dual suppression of pyroptosis and apoptosis." (PMID 41267084, 2025). "Moreover, a study using quantitative protein expression profiling concluded that upregulated S100A8 in serum can be a diagnostic biomarker in two groups of childhood leukemia (B and T cell acute lymphoblastic leukemia; B and T-ALL)." (PMID 37686186, 2023). "In addition, elevated S100A8 and S100A9 cause glucocorticoid resistance in pediatric acute lymphoblastic leukemia." (PMID 29955397, 2018). "In acute lymphoblastic leukemia (ALL), various serum proteins have been identified in recent years as candidate biomarkers including S100A8, coagulation factor XIII subunit A, and a panel of 9 serum-derived glycoproteins." (PMID 34360786, 2021). "In pediatric acute lymphoblastic leukemia (ALL), as expected, since normal lymphoid cells do not express S100A8 and S100A9, the expression levels of these genes were significantly lower than in AML." (PMID 33801279, 2021).
dermatitis (11 papers, 2017 to 2024). An inflammatory process affecting the skin. "In fact, the level of S100A8/A9 is related to skin barrier dysfunction; in specific dermatitis, upregulated S100A8/A9 expression exacerbates immune-induced damage, while the condition is improved with defects in MyD88." (PMID 29942307, 2018). "Th17 cell-associated genes, (i.e., S100a8, CAMP, BATF, IL-23A, LCN2, and HIF-1α) highly expressed in Nfkbiz−/− mice with dermatitis, were downregulated after antibiotic treatments." (PMID 28740238, 2017). "To determine whether EVEs decreased the expression of the TLR4 ligands of HMGB1 and S100A8 in a mouse model of TPA-induced skin inflammation, we applied topical TPA to the right ear five times at 3-day intervals and measured the effects of the EVEs and DXA." (PMID 39684233, 2024). "In this study, we found that EVEs decreased skin inflammation by reducing HMGB1 and S100A8 and decreasing TLR4 expression, which then inhibited pyroptosis." (PMID 39684233, 2024). "However, in this study, we observed robust Th17 responses as well as expression of IL-17A signature genes (i.e., S100a8, S100a9, CAMP, and LCN2) in the skin of Nfkbiz−/− mice with spontaneous dermatitis." (PMID 28740238, 2017). "Furthermore, IL-17A target genes (i.e., S100a9, S100a8, CAMP, and LCN2) were remarkably upregulated in the skin of Nfkbiz−/− mice with dermatitis." (PMID 28740238, 2017). "Thus, we hypothesized that EVEs decrease skin inflammation by reducing HMGB1, S100A8, and the TLR4/NF-κB/NLRP3 inflammasome pathway, which eventually decreases TPA-induced skin inflammation." (PMID 39684233, 2024).
hepatocellular carcinoma (11 papers, 2012 to 2025). A malignant tumor that arises from hepatocytes. "Strong experimental evidence indicates that S100A8/A9 overexpression in hepatocytes is associated with liver carcinogenesis as epidemiological studies showed a profound correlation of both proteins with high grade hepatocellular carcinoma in humans." (PMID 23241281, 2012). "S100A8/S100A9 co-expression in hepatocellular carcinoma cells promotes malignant progression by induction of ROS, down-regulation of p38 MAPK signaling, cell survival, and resistance to tumor necrosis factor (TNF)-α-induced apoptosis." (PMID 36609243, 2023). "Second, we examined the effects of vildagliptin and M20.7 on mRNA expression levels of inflammation-associated genes, such as S100A8, S100A9, and TNF-α, in human hepatoma HepG2 and monocytic HL-60 cells." (PMID 27759084, 2016). "Interestingly, elevated S100a8/a9 levels protected hepatocellular carcinoma cell lines from TNF-mediated apoptosis and promoted the production of ROS." (PMID 23241281, 2012). "In addition, S100A8 was found to promote oxidative stress by regulating neutrophil chemotaxis and activation, leading to telomere damage in hepatocytes, which accelerated the progression of liver disease and the formation of hepatocellular carcinoma." (PMID 40475761, 2025). "BIRC5, SPINK5, SPP1, CACYBP, RAET1E, and NR0B1 were significantly up-regulated, and S100A8 was significantly down-regulated in hepatocellular carcinoma samples based on TCGA-HCC dataset." (PMID 33568167, 2021). "In addition, overexpression of S100A8 in Huh 7 and MHCC-97H hepatoma cells resulted in increased cell proliferation, migration, and invasion." (PMID 31998802, 2020). "Furthermore, S100A8 overexpression in Huh7 and MHCC-97H hepatoma cell lines led to increased cell proliferation, migration, invasion, and tumor growth." (PMID 27462864, 2016). "For the S100A8 partnering protein S100A9, it was suggested that it is expressed by CCR2+ TAMs in hepatocellular carcinoma (HCC), where CCR2+ TAMs presented the same expression pattern as S100A9+ TAMs and were co-localized with CD31+ endothelial cells in areas of dense vascularisation." (PMID 34209679, 2021).
liver cancer (11 papers, 2011 to 2025). An epithelial or non-epithelial malignant neoplasm that arises from the liver. "In the diethylnitrosamine-induced HCC model, S100A8/A9 ablation impaired liver cancer progression by decreasing cancer cell proliferation." (PMID 34517344, 2021). "However, there are few reports about the relationship between the methylation level of S100A8 and the prognosis of liver cancer." (PMID 27462864, 2016). "Most S100 family members, such as S100A8 and S100A9, have already been reported to be involved in liver cancer." (PMID 40352930, 2025). "We then took an intersection of the Kcr proteins identified in liver cancer tissue quantitative analysis and hypoxic cell lines: CAT, S100A8, EEF2, and LMNA were co-identified." (PMID 35977926, 2022). "Members of the S100 calcium binding protein family, namely, S100A7, S100A8, S100A9, and S100A10, exert a momentous function in tumor growth and metastasis, such as breast and liver cancer." (PMID 36421685, 2022). "The upregulation of S100A8 and S100A9 correlates with poor differentiation of human liver cancer cells and tissues." (PMID 34517344, 2021). "Six genes (BIRC5, CACYBP, NR0B1, RAET1E, SPINK5, SPP1) were up-regulated in the liver cancer tissues compared to the normal tissues in the TCGA HCC dataset, and S100A8 was downregulated." (PMID 33568167, 2021). "Whether the crotonylation of CAT, S100A8, and EEF2 plays a vital role in liver cancer proliferation and the cellular response to hypoxia remains to be investigated." (PMID 35977926, 2022).